WEE1 (WEE1 G2 checkpoint kinase)
Diseases named in the same sentence as WEE1 in open-access papers (continued):
Sharing a sentence is not in itself a finding about the gene and the disease.
ovarian carcinoma (continued). "A similar approach has been conducted in experimental glioma and ovarian cancer using PARP1 inhibition plus temozolomide and WEE1 inhibition plus carboplatin, respectively." (PMID 38475864, 2024). "More recently, CCNE1 amplification has been proposed as a potential biomarker indicative of response to combined WEE1 inhibition and ATR inhibition in preclinical ovarian cancer and endometrial cancer models." (PMID 37457127, 2023). "The BET bromodomain inhibitor JQ1 synergized with the PARP inhibitor olaparib in BRCA1/2 wild-type ovarian cancer both in vitro and in vivo and was correlated with the suppression of both TOPBP1 and WEE1." (PMID 36139634, 2022). "It was previously reported that JQ1 synergized with olaparib in BRCA1/2 wild-type ovarian cancer both in vitro and in vivo and correlated with the suppression of TOPBP1 and WEE1." (PMID 36139634, 2022). "Targeting mitotic control, either by selective inhibition of CDK1 or aberrant activation of CDK1 via Wee1 inhibition, has been successful in increasing the efficacy of PTX in breast and ovarian cancers." (PMID 34370741, 2021). "Simultaneous treatment of ovarian cancer xenograft models with PARP and WEE1 inhibition was effective but poorly tolerated, while sequential administration retained efficacy with reduced toxicity." (PMID 32526907, 2020). "We therefore investigated the potential of Wee1 inhibition as chemopreventive strategy for mucosal precancer, included HNSCC tumor cell lines, and also related the findings to ovarian cancer cells as reference." (PMID 32047167, 2020). "Using real-time PCR, we found that silencing SMYD3 significantly decreased the mRNA levels of CCNA2, CCNB2, CCND2, CDK1 and CDK2 (p<0.05) but increased the mRNA levels of WEE1 (p<0.05), suggesting an essential role for SMYD3 in ovarian carcinoma proliferation." (PMID 31417652, 2019). "On the other hand, the WEE1 inhibitor MK1775 has been actively tested in leukemia and many solid tumors including ovarian cancer as mono- or combined therapy (clinicaltrials.gov)." (PMID 27558154, 2016). "Studies combining Wee1 inhibitors and PARP inhibitors are being explored in ovarian cancer (NCT05198804); however the overlapping hematologic toxicities of these two agents may limit combinatorial dosing." (PMID 40678577, 2025). "Many clinical trials, including trials evaluating drugs targeting ATR, ATM, WEE1, checkpoint kinase 1/2 (CHK1/2), BRCA1/2 and RAD51, have been designed to evaluate interference with DDR pathways to overcome platinum and PARPi resistance in ovarian cancer." (PMID 38539161, 2024). "The WEE1 inhibitor adavosertib with or without olaparib was investigated in a phase 2 non-comparative study in patients with epithelial ovarian cancer with documented progression on PARPis." (PMID 39796639, 2024). "WEE1 has emerged as an attractive target in epithelial ovarian cancer (EOC), but how EOC cells may alter their sensitivity to WEE1 inhibition remains unclear." (PMID 36378528, 2023). "In addition, HJURP was positively correlated with WEE1 in ovarian cancer according to GEPIA database, and protein level of WEE1 after silencing HJURP was also detected by WB." (PMID 35173547, 2022). "Moreover, inhibitory regulators such as p‐wee1, p21waf1/cip1, and p27kip1 were increased in the MTHFD2 silencing ovarian cancer cells." (PMID 34231329, 2021).
ovarian carcinoma (continued). "In addition, in vitro experiments showed that Wee1 silencing in SKOV3 and OVCAR8 ovarian cancer cells significantly reduced proliferation." (PMID 33224881, 2020). "Notably, our study is among the first to propose Naringin as a natural compound capable of simultaneously targeting CDK1 and WEE1, based on both docking affinity and dynamic binding stability—an aspect not explored in prior ovarian cancer studies." (PMID 41009727, 2025). "Accordingly, we investigated the effects of PLK1 and WEE1 inhibition in BRCA-WT and BRCA-Mut HGSOC models, focusing on DNA repair dependency, cell cycle regulation, and differential drug sensitivity, to identify therapeutic strategies for BRCA-WT and HRP ovarian cancers." (PMID 41354716, 2025). "In addition, a phase I/II clinical trial of the WEE1 inhibitor ZN-c3 combined with niraparib was conducted in patients with platinum-resistant ovarian cancer (NCT05198804), but no results have been published." (PMID 38539161, 2024). "In fact, WEE1 expression in ovarian cancer stem-like cells could be resorted by transcription factor NANOG via modulating the negative impact miR-424/503 on WEE1 transcripts." (PMID 39273409, 2024). "Moreover, after normalization by the corresponding vehicle-treated group, tumor growth under AZD1775 treatment was highly correlated with ODF2L expression in the ovarian cancer PDX, indicating a role for ODF2L in affecting the response to WEE1 inhibition in EOC." (PMID 36378528, 2023). "To further validate the relationship between ODF2L and the response to WEE1 inhibition in EOC, we examined the correlation of ODF2L levels, CDK1 activity, and cell viability in a panel of AZD1775-treated primary EOC cells derived from 57 tissue samples from patients with ovarian cancer." (PMID 36378528, 2023). "Alternatively, similar analyses in comparing these preclinical models could be applied to other drugs in ovarian cancer treatment, such as paclitaxel, poly (ADP-ribose) polymerase (PARP) inhibitors and other drugs currently in preclinical studies such as HIF, WEE1 and TGFß inhibitors." (PMID 34521878, 2021).
glioma (61 papers, 2011 to 2026). A benign or malignant brain and spinal cord tumor that arises from glial cells (astrocytes, oligodendrocytes, ependymal cells). "In this study, we focused on the association between miR-138-5p and WEE1 in order to explore the potential mechanism of the antitumor effects of miR-138-5p in glioma." (PMID 35127343, 2022). "miR-138-5p regulates proliferation, migration, and invasion of glioma cells by targeting WEE1, which is associated with poor prognosis of glioma patients." (PMID 35127343, 2022). "Expression of WEE1 has been found to be associated with poor prognosis in a variety of tumor types including gliomas." (PMID 34295296, 2021). "In terms of prognostic analysis, consistent with our previous results, high expression of CDK4, HMGB2, and WEE1 could lead to poor prognosis of glioma; however, gliomas with high expression of SMC3 and GADD45G were linked to longer survival." (PMID 34123852, 2021). "Our analysis predicted a significant association between miR-128 and the protein kinase WEE1, which we subsequently validated experimentally by showing that the over-expression of the naturally under-expressed miR-128 in glioma cells resulted in the inhibition of WEE1 in glioblastoma cells." (PMID 21358821, 2011). "WEE1 is a protein kinase whose expression increases with the increase of malignant degree of glioma." (PMID 39707577, 2024). "Specifically, the relative expression levels of CDK1 and CyclinB1 were reduced, while in glioma cells, the expression levels of Wee1 and p21 were upregulated in GBM8401 cells." (PMID 37242425, 2023). "Early findings that Wee1 inhibition by the unspecific inhibitor PD0166285 radiosensitizes glioma stem cells (CD133 enriched glioma neurospheres) were contradicted by a study using AZD1775 (and glioma cell lines enriched for neuronal stem cells)." (PMID 35251998, 2022). "Survival analysis further suggested regulatory correlations: elevated expression of FAM18A-AS1 and miR-21 was associated with poor prognosis in low-grade glioma, and high expression of EGFR, WEE1, MAP2K3, JA1, and EPHA2 was associated with poor prognosis." (PMID 35296768, 2022). "miR-138-5p and WEE1 G2 checkpoint kinase (WEE1) RNA and protein expression levels in glioma tissues were detected with qRT-PCR and western blotting, respectively." (PMID 35127343, 2022). "The effects of miR-138-5p and WEE1 on glioma cell migration and invasion were investigated using Transwell assays." (PMID 35127343, 2022). "Overexpression of WEE1 reverses the inhibitory effect of miR-138-5p on the proliferation and invasion of glioma cells and induced death." (PMID 35127343, 2022). "WEE1 is overexpressed in pediatric high-grade gliomas, with increasing expression positively correlated with malignancy." (PMID 35127343, 2022). "Future studies include fully describing the mechanism of miR-138-5p and WEE1 in glioma and exploring more candidate therapeutic targets of miR-138-5p." (PMID 35127343, 2022). "WEE1 expression was found to be statistically significant in all glioma cell lines, but only when compared to hRNA controls (4.75, 2.79, 2.24)." (PMID 36142793, 2022). "We confirmed that the ectopic expression of WEE1 reversed the inhibitory effect of miR-138-5p overexpression on proliferation, migration, and invasion of glioma cells." (PMID 35127343, 2022). "In conclusion, our study demonstrated that WEE1 is a downstream functional effector of miR-138-5p in glioma cells, and miR-138-5p regulates the development and progression of glioma through WEE1." (PMID 35127343, 2022). "LINC00470 in GBM-exo can bind to miR-580-3p in glioma cells to regulate WEE1 expression and activate the PI3K/AKT/mTOR pathway, thereby inhibiting autophagy and enhancing the proliferation of glioma cells." (PMID 33663509, 2021). "In the cellular experiments, we found a massive decrease in miR-580-3p expression and a significant increase in WEE1 expression in glioma cells." (PMID 33663509, 2021).
glioma (continued). "It has been well-documented that overexpression of WEE1 promotes the proliferation and drug resistance of glioma cells." (PMID 33663509, 2021). "WEE1 inhibitor can selectively inhibit the proliferation of glioma and hepatocellular carcinoma cells with ATRX mutations, which indicates that the synthetic lethal interaction between ATRX and WEE1 can be applied in an extensive range of tumors." (PMID 32883316, 2020). "For example, in glioma, miR-526b-5p and miR-548b-3p acted as tumor suppressors by targeting WEE1 and MTA2, respectively." (PMID 33221765, 2020). "Some studies found over-expression of WEE1 in gliomas and interfering with WEE1 expression has therapeutic potential in glioblastomas." (PMID 30115812, 2018). "An in silico analysis found that WEE1 is highly expressed in high grade glioma compared to normal brain tissue and siRNA-mediated depletion of WEE1 led to abrogation of G2 checkpoint-mediated cell cycle arrest and increased cell death." (PMID 27043632, 2016). "For example, Dasatinib, a small-molecule tyrosine kinase inhibitor, has been shown in vitro to effectively suppress the malignant phenotype of glioma stem cells when combined with a WEE1 inhibitor, and it exhibited higher predicted sensitivity in the high-risk group." (PMID 41331166, 2025). "Another study has shown that miR-526b targets WEE1 and suppresses glioma cells." (PMID 37828032, 2023). "However, the role of WEE1 in glioma was also found to be connected to the MGMT status, which was not considered in our analysis." (PMID 37400829, 2023). "There are some studies that have shown that WEE1 is overexpressed in gliomas." (PMID 35127343, 2022). "miR-138-5p suppresses glioma progression by regulating WEE1." (PMID 35127343, 2022). "WEE1 promotes the proliferation, migration, and invasion of glioma cells." (PMID 35127343, 2022). "We investigated whether WEE1 can mediate the effects of miR-138-5p on proliferation, invasion, and death in glioma cells." (PMID 35127343, 2022). "We found that miR-138-5p may play a tumor-suppressive role by targeting WEE1, which acts as an oncogene in glioma." (PMID 35127343, 2022). "In this study, we explored whether miR-138-5p affects the biology of glioma by regulating WEE1 expression." (PMID 35127343, 2022). "In addition, a recent study also confirmed the downregulated miR-526b-3p level in both glioma tissues and cell lines, and that enforced miR-526b-3p can arrest glioma tumorigenesis and progression by targeting WEE1." (PMID 35418162, 2022). "In addition, study found that targeting G2 checkpoint kinase WEE1 can attenuate TMZ resistance in gliomas." (PMID 35615996, 2022). "Consequently, Wee1 is often highly expressed in many cancers including breast and lung cancers, glioma, melanoma, leukemia, osteosarcoma, and squamous cell carcinoma." (PMID 35251998, 2022). "Moreover, reintroduction of WEE1 partially abrogated miR-138-5p-induced suppression of motility and invasion in glioma cells." (PMID 35127343, 2022). "Additionally, five DDRGs (CDK4、HMGB2、WEE1、SMC3 and GADD45G) were selected to construct a DDRGs signature for glioma, stratifying patients into low- and high-risk groups." (PMID 34123852, 2021). "In this study, we demonstrated that LINC00470 secreted by serum exosomes from glioma patients can bind miR-580-3p to regulate WEE1 expression and activate PI3K/AKT/mTOR signaling pathway, thus inhibiting glioma cell autophagy and promoting glioma cell proliferation." (PMID 33663509, 2021). "The results demonstrated that LINC00470 in serum exosomes from glioma patients, through competing with WEE1 to bind miR-580-3p, could augment proliferation and impair the autophagy of glioma cells via activating PI3K/AKT/mTOR signaling pathway." (PMID 33663509, 2021). "LINC00470 in GDE could competitively bind to miR-580-3p in glioma cells to modify WEE1 expression and activate the PI3K/AKT/mTOR pathway, thus suppressing autophagy and strengthening the proliferation of glioma cells." (PMID 34887381, 2021).
glioma (continued). "Moreover, Wee1 was found to be overexpressed and functionally important in medulloblastoma, and a high expression of Wee1 was described in glioma." (PMID 34639030, 2021). "WEE1 activation is considered to be a vital driver of G2-M transition through inhibiting phosphorylation of Cdc2, and WEE1 inhibition has been verified to suppress glioma progression in adult nude mouse models via advancing mitosis in cells with damaged DNA." (PMID 33663509, 2021). "A recent study was reported that the lncRNA LINC00470 in GBM exosomes could inhibit autophagy and enhance the proliferation of glioma cells through binding to miR-580-3p to regulate WEE1 expression." (PMID 34454479, 2021). "Consistently, in our study, miR-580-3p was reported as a tumor suppressor gene that could impede glioma cell proliferation and augment glioma cell autophagy, while WEE1 could reverse those effects." (PMID 33663509, 2021). "Moreover, patients with high WEE1 expression had poor survival than did patients with low WEE1 expression in grade III gliomas." (PMID 31921517, 2020). "It has been reported that WEE1 is closely related to the growth, invasion and migration of glioma." (PMID 31921517, 2020). "Moreover, re-introduction of hsa-miR-524-5p in glioma cells showed that Ttk, Cdk2 and Wee1 expression were reduced in LN229 cells via transfecting hsa-miR-524-5p." (PMID 24194606, 2013). "Furthermore, inhibiting WEE1 expression in glioma cells resulted in cell death." (PMID 38231277, 2024). "Recently, ABCC3 has been included in gene signatures (ABCC3, CD44, TNFRSF1A, and MGMT24; ABCC3, SMC4, EMP3, WEE1, and HIST1H2BK44) that classify glioma patients in agreement with therapeutic response to chemotherapeutic agents, including TMZ." (PMID 36585418, 2022). "The forest map of Cox regression analysis indicated that SMC3 and GADD45G were positively correlated with the prognosis of patients with glioma, whereas CDK4, WEE1, and HMGB2 were negatively correlated with prognosis." (PMID 34123852, 2021). "More specifically, we identified LINC00470 can bind to miR-580-3p to regulate WEE1 and thereby regulate PI3K/AKT/mTOR pathway, ultimately mediating cell autophagy in glioma." (PMID 33663509, 2021). "Alternatively, non-invasive techniques such as focused ultrasound with microbubbles, under ongoing clinical evaluation in gliomas, may improve the BBB penetrance of WEE1 inhibitors." (PMID 41585496, 2026). "The lifting of PRC2-mediated repression unleashes a cascade of pro-tumorigenic events: formerly silenced oncogenic factors become active, which in turn drive the formation of glioma-specific super-enhancers and up-regulate oncogenes such as EGFR, miR-21, and WEE1." (PMID 41154382, 2025). "In contrast, another study found that glioma stem cells (unlike neuronal progenitor cells) were sensitive to Wee1 inhibition alone." (PMID 35251998, 2022). "Moreover, analysis of genes and proteins that interact with KIF18A showed that several molecules related to cell cycle and cell division, such as RRP7A, ANAPC4, WEE1, CDC20, and NDC80, were enriched in glioma." (PMID 35591854, 2022). "The DDRGs signature composed of CDK4, HMBG2, WEE1, SMC3 and GADD45G could accurately predict the prognosis of gliomas." (PMID 34123852, 2021). "Utilizing expression data from primary glial tumors, we confirmed that WEE1 is strongly over-expressed in gliomas compared to non-tumor control cases." (PMID 21358821, 2011). "However, a miR-138-5p mimic transfection did not significantly reduce the luciferase activity and WEE1 protein expression in glioma cells." (PMID 35127343, 2022). "The resulting phenotypes of Wee1 siRNA resulted in dramatic inhibition of cellular proliferation as measured by MTS reagent in H1299 non-small cell lung (NSCLC) and Daoy glioma cell lines but did not affect growth of A549 NSCLC, D54MG glioma or A2780 ovarian tumor lines." (PMID 24927813, 2014).